CLDN18 (claudin 18)
Diseases named in the same sentence as CLDN18 in open-access papers (continued):
Sharing a sentence is not in itself a finding about the gene and the disease.
gastric cancer (continued). "Tissue microarrays constructed using primary lesions and nodal metastases of 106 advanced gastric cancers revealed CDH17 and CLDN18 expression in 98 positive cases of 106 (92%)." (PMID 27580354, 2016). "Currently, the most accredited modality for identifying CLDN18 positive vs. negative cases in gastric cancer is based on calculating the percentage of 2 +/3 + positive tumor cells, considering positive those cases with ≥ 75% of 2 +/3 + cells." (PMID 40835751, 2025). "A prior study demonstrated that CLDN18 expression was significantly reduced in gastric cancer cases with PM compared to those without." (PMID 40205072, 2025). "In conclusion, our study highlighted a groundbreaking investigation into the mechanism of the CLDN18.2-directed ADC, focusing on the crucial role of autophagy, providing a novel insight to treat gastric cancer by the combination of CLDN18.2-directed ADC and autophagy inhibitor." (PMID 39227365, 2024). "The CLDN18-ARHGAP fusion gene-derived neoantigen has good immunogenicity, and neoantigen-reactive T cells induced by it have specific and robust anti-tumor capacity both in in vitro coculture models and in vivo xenograft gastric cancer models." (PMID 39164472, 2024). "Considering the relatively low PD-L1 expression and moderate CLDN18 positivity regardless of PD-L1 status, CLDN18 is a promising therapeutic target for patients with PD-positive gastric cancer who exhibit low PD-L1 expression." (PMID 38724721, 2024). "Because of its clinical importance and the lack of data, we examined the expression of CLDN18 in both primary tumors and PD to determine the applicability of zolbetuximab in patients with PD-positive gastric cancer." (PMID 38724721, 2024). "In a previous study, CLDN18 expression was significantly lower in gastric cancer with PD than those without PD." (PMID 38724721, 2024). "Among 20 cancers of unknown primary examined, two had the CLDN18:ARHGAP26 fusion, which has been reported in gastric carcinomas and may suggest the origin of the unknown primary tumor." (PMID 38800398, 2024). "The expression of claudin-4 in gastric cancer was negatively associated with DNA methylation, and miRNA can lead to decreased expression of claudin-18 by binding to its 3'-UTR region and subsequently promote the proliferation, migration, and invasion of gastric cancer cells." (PMID 28350854, 2017). "In this study, we selected CDH17 and CLDN18 through mining of systemic microarray gene expression data, based on their high frequency of expression in gastric cancer tissues and absence of expression in other major vital organs." (PMID 27580354, 2016). "IHC scores of CDH17, CLDN18, and CLDN7 expression levels were evaluated semi-quantitatively in TMA-mounted primary lesions (IHC score (Pr)) and lymph node metastases (IHC score (LN)) taken from 106 cases of advanced gastric cancers." (PMID 27580354, 2016). "In this study, multiple gene expression arrays of 42 systemic normal tissue samples and 56 gastric cancer samples were used to investigate two adhesion molecules, cadherin 17 (CDH17) and claudin 18 (CLDN18), which are intestinal and gastric markers, respectively." (PMID 27580354, 2016). "The Ki-67 labeling index of gastric cancer at the invasive front was inversely correlated with the claudin-18 level, but that at the mucosal lesion was not correlated." (PMID 24073219, 2013). "An immunogenic peptide specifically targeting CLDN18-ARHGAP fusion gene was generated to induce neoantigen-reactive T cells, which was proved to have specific and robust anti-tumor capacity both in in vitro coculture models and in vivo xenograft gastric cancer models." (PMID 39164472, 2024).
gastric cancer (continued). "Also, gastric cancer cell with CLDN18-ARHGAP fusion gene could activate PI3K/AKT-mTOR-FAS signaling, which enhances free fatty acid production of gastric cancer cells to favor the survival of Treg cells and contribute to immune suppression." (PMID 39164472, 2024). "Importantly, after CLDN18-ARHGAP26 was introduced, considerable resistance to 5-fluorouracil and oxaliplatin was observed in a number of gastric cancer cell lines, which may account for the poor drug response of patients harboring this fusion product." (PMID 36620607, 2022). "In gastric cancer, ARHGAP26 is fused with claudin-18 gene (CLDN18), and the translated abnormal fusion protein regulates the development of gastric cancer, while circular RNA ARHGAP26 (circ-ARHGAP26) modulates microRNA through a “sponge” mechanism to affect the progression of gastric cancer." (PMID 34716859, 2022).
pancreatic cancer (29 papers, 2008 to 2025). "In pancreatic cancer, higher CLDN18.2 expression is preferentially associated with well-differentiated carcinomas and improved patient survival compared to low-expressing cases." (PMID 41019366, 2025). "For example, antibodies against CLDN18 (encoding for the tight junction protein Claudin 18) are currently under development in gastric and pancreatic cancer." (PMID 36975409, 2023). "In a prior study examining 160 surgically treated pancreatic cancer patients, survival outcomes were associated with CLDN18 expression." (PMID 37629433, 2023). "Until clinical trial data is released for pancreatic cancer, pathologists should report CLDN18 scoring following both modalities, thus reporting separately the percentage of 0, 1 +, 2 +, and 3 + cells and also the H-score." (PMID 40835751, 2025). "In an ongoing phase I clinical trial (NCT05009966), 33 patients with advanced, heavily pretreated CLDN18.2-positive gastric or pancreatic cancer received SYSA1801 monotherapy." (PMID 41019366, 2025). "Bispecific antibodies, such as anti-CD3/mesothelin and CD3/claudin-18.2, have demonstrated potent cytotoxic activity in preclinical pancreatic cancer models and are progressing into early-phase clinical trials." (PMID 40895848, 2025). "It is noteworthy that, the two scFv sequences (i.e., anti-CD40 scFv and anti-CLDN18.2 scFv) possess the ability to recognize both human macrophages and pancreatic cancer cells." (PMID 38468289, 2024). "To align our research with clinical relevance, we thus selected anti-CD40 scFv and anti-CLDN18.2 scFv sequences that enable recognize macrophages and pancreatic cancer in human." (PMID 38468289, 2024). "This association is supported by several previous reports demonstrating that CLDN18 is overexpressed in well-differentiated pancreatic cancer and its precursors." (PMID 37629433, 2023). "A phase I study of LY011 for CLDN18.2-positive patients with advanced GC and pancreatic cancer is now ongoing (NCT04977193 and NCT04966143)." (PMID 38136288, 2023). "Lower rates of CLDN18 positivity were recorded in comparison with those reported in gastroesophageal and bilio-pancreatic cancers [18 20 21 22 25 26 28 42]." (PMID 35925388, 2022). "AUC plots demonstrated that CLDN1 and CLDN18 represent potential predictors of thyroid cancer, and CLDN4 and CLDN18, predictors of pancreatic cancer." (PMID 29050243, 2017). "This suggests that in human pancreatic cancer cells claudin-18 is primarily regulated at the transcriptional level via specific PKC signaling pathways and modified by DNA methylation." (PMID 22559840, 2012). "The upregulation of claudin-18 by TPA in human pancreatic cancer cell lines can be prevented by inhibitors of PKCδ, PKCε, and PKCα, whereas the upregulation of claudin-18 by TPA in hTERT-HPDE cells is prevented by inhibitors of PKCδ, PKCθ, and PKCα." (PMID 22559840, 2012). "The results generated from these sessions are summarized in this manuscript and are proposed as consensus recommendations for evaluating and scoring CLDN18 immunohistochemical staining in pancreatic cancer specimens and we describe our experience and our recommendations below." (PMID 40835751, 2025). "Thus, we first construct KPC pancreatic cancer cells with stable, high CLDN18.2 expression, as confirmed by flow cytometry analysis of the sorted KPC cells." (PMID 38468289, 2024). "Considering CLDN18 as a potential therapeutic target for pancreatic cancer, our results may be beneficial in selecting subjects for CLDN18-targeted treatment in the future." (PMID 37629433, 2023). "ASP2138 showed anti-tumor activity against CLDN18.2-expressing gastric or pancreatic cancer cells." (PMID 38136288, 2023). "Thus far, many of the 27 members of the claudin family, including claudin-18.2 and claudin-4, have significantly aberrantly expression in pancreatic tumors." (PMID 36959784, 2023).
pancreatic cancer (continued). "We assessed the clinical characteristics of patients with CLDN18.2-overexpressing pancreatic cancer to identify patients who might benefit from CLDN18-targeted treatment." (PMID 37629433, 2023). "The lead molecule, anti-CLDN18.2 hu7v3-Fc, demonstrated enhanced in vitro and in vivo anti-tumor activities, compared to the benchmark Zolbetuximab in CLDN18.2-positive gastric and pancreatic tumor cells." (PMID 35837391, 2022). "The ectopic expression in pancreatic cancer tissues was mainly CLDN18-001." (PMID 32668412, 2020). "In contrast, ectopic overexpression of CLDN18 was observed in pancreatic cancer." (PMID 32668412, 2020). "However, the bispecific and diabody did display better cell killing of the gastric KATO-III/CLDN18.2 cells than the pancreatic cancer cell line, BxPC3/hCLDN18.2." (PMID 31182754, 2019). "Notably, CD133-targeted CAR-T cells have produced stable disease or partial response in subgroups of patients with pancreatic cancer, whereas CLDN18.2-directed CAR-T cells have shown good disease control rates in gastric, pancreatic, and gastro-esophageal malignancies." (PMID 40974479, 2025). "The evidence regarding CLDN18 expression in pancreatic tissues and PDAC paves promising horizons towards adopting similar approaches in the near future for patients affected by pancreatic cancer, pending the results of ongoing clinical trials." (PMID 40835751, 2025). "We report on the preclinical development of a CLDN18.2-targeting CAR-T therapy showing effectiveness in patient models with CLDN18.2-positive gastric, esophageal, and pancreatic tumors." (PMID 39321207, 2024). "Against both gastric and pancreatic cancer cell lines, DR30318 shows better TDCC potential especially against low or moderate CLDN18.2 expressing cells." (PMID 38554200, 2024). "Among them, pancreatic cancer cells in the cluster 8 with TIMP1+/FN1+ showed the strongest resistance, while the cluster 1 with CLDN18-/CEACAM5- and the cluster 7 with HSPA6+/NEAT1+ showed milder resistance." (PMID 38343537, 2024). "Preliminary data from phase I clinical trial (NCT03874897) demonstrated that CLDN18.2-targeted CAR-T cells were safe and showed some antitumor activities in advanced gastrointestinal cancer, including pancreatic cancer." (PMID 37046312, 2023). "For example, an anti-claudin-18.2 mAb is undergoing clinical study for the use in the treatment of gastric (phase III study) and pancreatic cancer (phase II study) [NCT03504397; NCT03816163]." (PMID 31426497, 2019). "Of note, although significant differences and tissue-related suggestions exist between gastric and pancreatic cancer specimens, no specific recommendations on CLDN18 expression evaluation and assessment have been proposed to date for this tumor type." (PMID 40835751, 2025). "Contrarily, another investigation involving 111 pancreatic cancer patients found no prognostic correlation tied to CLDN18 expression patterns." (PMID 37629433, 2023). "In conclusion, CLDN18 overexpression is correlated with several clinicopathological features, but not with prognosis in pancreatic cancer." (PMID 37629433, 2023). "Taken together, our data indicate that targeting CLDN18.2 with an ADC or bispecific modality could be a valid therapeutic approach for the treatment of gastric and pancreatic cancer." (PMID 31182754, 2019). "In subcutaneous xenografts of human pancreatic cancer cells models, Claudin-18 failed to achieve efficient gene transfer but Mucin-4 was found very potent." (PMID 23088623, 2012). "Interestingly however, CLDN18 and MUC4 achieved the best results in terms of efficiency and specificity in vitro and could be suitable for specific gene transfer in pancreatic tumor cells." (PMID 23088623, 2012).
GEJ adenocarcinoma (22 papers, 2017 to 2026). "The evaluation of claudin-18 (CLDN18) by immunohistochemistry (IHC) has already entered routine diagnostic activity as a predictive biomarker for patients with gastric and gastroesophageal junction adenocarcinomas." (PMID 40835751, 2025). "The CLDN18.2-targeted antibody zolbetuximab is approved for the treatment of locally advanced unresectable or metastatic HER2-negative gastric or GEJ adenocarcinoma in adults with CLDN18.2-positive tumors." (PMID 41488290, 2026). "CLDN18 expression tested by IHC has already entered daily clinical practice for selecting patients with locally advanced and metastatic gastric and gastroesophageal junction adenocarcinomas for anti-CLDN18.2-targeted therapy." (PMID 40835751, 2025). "The expert working group recommendations highlight the importance of reflex testing for HER2, MMR and/or MSI, CLDN18, and PD-L1 in all patients at first diagnosis of G/GEJ adenocarcinoma." (PMID 39727695, 2024). "Another retrospective study using the same assay and cut-off values for CLDN18.2 positivity reported a prevalence of 33.4% in a cohort of 350 evaluable White patients with advanced G/GEJ adenocarcinoma from Italy." (PMID 38954176, 2024). "Actually, there is just one chimeric mAb in review by the FDA and EMA called Zolbetuximab against claudin 18.2 to treat gastric or gastroesophageal junction adenocarcinoma." (PMID 38534210, 2024). "There are limited data on the global prevalence of CLDN18.2 positivity in tumors of patients with LA unresectable or mG/GEJ adenocarcinoma." (PMID 38954176, 2024). "Previous work on the co-expression of CLDN18.2 and other biomarkers in advanced esophagogastric adenocarcinoma has been biased by the use of different antibodies and positivity thresholds." (PMID 38339430, 2024). "Further research is needed to establish if there is a link between CLDN18.2 status and Lauren classification in patients with LA unresectable or mG/GEJ adenocarcinoma." (PMID 38954176, 2024). "Twenty-eight patients with previously treated advanced G/GEJ adenocarcinoma that was CLDN18.2-expressing were enrolled into four treatment arms." (PMID 36607429, 2023). "Part 2 cohort included patients both with advanced G/GEJ adenocarcinomas and CLDN18.2 expression (IHC 2+/3+ ≥ 40%)." (PMID 38136288, 2023). "At present, a phase I clinical study of patients with CLDN18.2-positive GC and GEJ adenocarcinoma is ongoing (NCT04260191)." (PMID 35642043, 2022). "CLDN18.2 expression was positive (defined as ≥ 75% of tumor cells showing moderate to strong membranous claudin 18 (CLDN18) staining) in 38% of patients with locally advanced unresectable or metastatic gastric or GEJ adenocarcinoma screened for participation in clinical trials." (PMID 41488290, 2026). "The Claudin 18 IHC assay detects both isoforms of CLDN18: the CLDN18.1 isoform, which is predominantly expressed in normal and neoplastic lung tissue, and CLDN18.2, which is expressed in normal gastric tissue, gastric/GEJ adenocarcinoma, and other malignancies." (PMID 39727695, 2024). "Studies have shown approximately 40–50% of the population to show CLDN18.2 positivity for GAC, GEJ adenocarcinoma, and EAC." (PMID 38392051, 2024). "A strength of this analysis is that the SPOTLIGHT and GLOW studies represent the largest sources to date for data on the global prevalence of CLDN18.2 positivity in patients with HER2-negative, LA unresectable or mG/GEJ adenocarcinoma." (PMID 38954176, 2024). "Similar to the general population of patients with advanced esophagogastric adenocarcinoma, MSI/dMMR occurs in roughly 5% of CLDN18.2-positive tumors." (PMID 38339430, 2024). "Zolbetuximab plus CAPOX represents a potential new first-line therapy for patients with CLDN18.2-positive, HER2-negative, locally advanced unresectable or mG/GEJ adenocarcinoma." (PMID 37524953, 2023). "CLDN18.2-positive advanced treatment-naïve GAC and GEJ adenocarcinoma patients were enrolled." (PMID 38392051, 2024).
GEJ adenocarcinoma (continued). "In 2023, investigators also published the SPOTLIGHT trial, a randomized phase III trial also involving CLDN18.2-positive (≥75% of tumor cells with moderate-to-strong CLDN18 membranous staining), HER2-negative, locally advanced unresectable, or metastatic gastric/GEJ adenocarcinoma patients." (PMID 38339430, 2024). "GLOW (closed enrollment), a global, double-blind, phase 3 study, examined zolbetuximab, a monoclonal antibody that targets CLDN18.2, plus capecitabine and oxaliplatin (CAPOX) as first-line treatment for CLDN18.2-positive, HER2-negative, locally advanced unresectable or mG/GEJ adenocarcinoma." (PMID 37524953, 2023). "Claudin 18 (CLDN18) overexpression is a biomarker that is not currently in clinical use in Canada that predicts response to anti-CLDN18.2 therapy and occurs in 38–43% of patients with G/GEJ adenocarcinoma." (PMID 39727695, 2024). "It was granted a priority review by the Food and Drug Administration (FDA) in 2023 for patients with locally advanced, inoperable or metastatic GC/GEJ with moderate to strong expression of CLDN18.2, HER2 negative GC or GEJ adenocarcinoma." (PMID 38383390, 2024). "Our results suggest ZOL-FO is not cost-effective as the first-line treatment for CLDN18.2-positive, HER2-negative advanced G/GEJ adenocarcinoma compared with PLB-FO." (PMID 37719841, 2023). "Zolbetuximab, a CLDN18.2-targeting antibody, plus chemotherapy improved survival outcomes in patients with CLDN18.2-positive, human epidermal growth factor receptor 2 (HER2)-negative mG/GEJ adenocarcinoma." (PMID 41840238, 2026).